FHIT (fragile histidine triad diadenosine triphosphatase)
Diseases named in the same sentence as FHIT in open-access papers (continued):
Sharing a sentence is not in itself a finding about the gene and the disease.
tumor (continued). "As previously demonstrated for the oncosuppressor gene FHIT, analysis of MGMT expression in sarcoid tissues and a sarcoid-derived fibroblast cell line further suggests that oncosuppressor silencing may be also involved in BPV-induced equine tumours." (PMID 23140380, 2012). "Interestingly, although FHIT overexpression suppresses tumorigenicity both in vitro and in vivo, the hydrolase “dead” FHIT mutant also suppresses tumorigenicity in vivo, indicating that the hydrolase activity of FHIT is not required for tumor suppression." (PMID 23109895, 2012). "No staining for FHIT protein was observed in 7 out of 9 tumour cases (80%)." (PMID 22424615, 2012). "Primary tumours (76%) showed LOH encompassing FHIT and 70% were negative for Fhit protein." (PMID 12771912, 2003). "Thus, the catalytically dead mutant that binds substrate well, FHIT H96N, displays more extensive oxidative damage, activation of apoptosis and suppression of tumors, confirming that enzymatic activity is not required for its tumor suppressive function." (PMID 24901304, 2014). "Both 30 mg/kg and 60 mg/kg CHIR99021 significantly reduced the tumor volume and wet weight of FHIT−/− HCC827 tumor xenografts, whereas the drug did not have apparent antitumor effects on the parental HCC827 tumor xenografts." (PMID 39762409, 2025). "Given that FHIT methylation was only seen in ATL patient samples, and not asymptomatic or TSP/HAM patient samples, again confirms its specific role in tumor initiation and/or maintenance." (PMID 34092254, 2021). "Notably, similarly to its FRA3B/FHIT counterpart, the role of FRA16D/WWOX in cancer has been controversial, resulting in their categorisation by some as “non-classical” tumour suppressor genes." (PMID 34210081, 2021).
cancer (137 papers, 1998 to 2025). A tumor composed of atypical neoplastic, often pleomorphic cells that invade other tissues. "The methylation tends to suppress the expression of the FHIT, allowing the generation and accumulation of mutations in tumors that drive the evolutionary development of cancer." (PMID 36831487, 2023). "Further evidence supports that FHIT is a genomic ‘caretaker’ whose loss initiates genome instability and the onset of cancer development in humans." (PMID 37634038, 2023). "Either AGTR1 or FHIT methylated cases were significantly associated with HPV-positive cancers with 92.0% sensitivity (P < 0.001)." (PMID 36344942, 2022). "Studies have shown that loss of FHIT expression can direct a cell into a more genetically favorable cancer inducing phenotype." (PMID 34092254, 2021). "In fact, reduced FHIT expression has been suggested to drive initiation of the specific cancer mutational signature." (PMID 34092254, 2021). "It is also likely, given the importance of FHIT loss in cancer, that transcriptional factors, lncRNAs, mRNAs, or circRNAs affect FHIT expression and remain to be identified." (PMID 35663592, 2021). "Over 50% of cancers show loss of FHIT expression; and it is believed that this loss is one of the earliest initiation events in the establishment of cancers." (PMID 34092254, 2021). "Although it was identified more than 20 years ago, questions remain as to how FHIT loss contributes to cancer, and conversely, how FHIT acts to maintain genome integrity and suppress malignancy." (PMID 29282095, 2017). "We have thus proposed that loss of FHIT expression underlies development of the ubiquitous signature 5 mutations in human cancers." (PMID 29254236, 2017). "We conclude that FHIT loss is a molecular determinant for signature 5 mutations, which occur in all cancer types early in cancer development, are clock-like, and accelerated by carcinogen exposure." (PMID 29254236, 2017). "We analyzed the association between FHIT expression and cancer susceptibility of gastric normal mucosa in 10 studies with 1113 cancers and 518 controls." (PMID 29296239, 2017). "Deletions, loss of expression, and other alterations of the FHIT locus have been frequently observed in a variety of cancers and in premalignant lesions." (PMID 27977694, 2016). "In light of our findings, it will be useful to stratify cancer cohorts by both FHIT and A3B expression to more accurately predict which cancers are most susceptible to APOBEC-induced hypermutation." (PMID 25401976, 2015). "A cooperative role in APOBEC3B mutagenesis is furthermore attributed to the tumor suppressor fragile histidine triad protein (FHIT), which is known to cause DNA damage upon loss of protein activity in normal and cancer cells." (PMID 26097867, 2015). "Alterations at the FRA3B CFS, centered within the FHIT gene locus, leads to partial or full loss of FHIT gene and protein expression in >50% of sporadic cancers, many of which exhibit APOBEC signature mutations." (PMID 25401976, 2015). "FHIT harbors one of the most common fragile sites in the genome called FRA3B and is often associated with chromosomal deletions in various cancer cell lines and tumors." (PMID 25152695, 2014). "Conversely, cancer cells deficient of FHIT expression cannot protect FDXR from proteasomal degradation and escape apoptosis as they are less sensitive to oxidative stress." (PMID 24901304, 2014). "The Fragile Histidine Triad (FHIT) gene spans the FRA3B locus on chromosome 3p14.2 and alterations at this common fragile site are associated with many types of cancer." (PMID 25340791, 2014). "The FHIT protein is thought to have a role in tumor suppression based on its expression and function in human cancers as well as its role in tumor development in the FHIT-deficient mouse model." (PMID 25340791, 2014).
cancer (continued). "FHIT encodes a tumor suppressor protein whose loss is implicated in a large fraction of cancers; in fact, its deletion or loss of expression has been reported in head and neck, gastrointestinal, cervical, lung, breast, and hematopoietic tumors." (PMID 24223161, 2013). "Despite the frequent suppression of WWOX, FHIT and p73 expression in numerous cancers, complete gene inactivation by the deletion of one allele and a second mutation or homozygous deletion is extremely rare." (PMID 24137446, 2013). "FHIT is a tumour suppressor gene and many lines of evidence support the association between HPV infection and FHIT expression alteration in different cancer types." (PMID 22424615, 2012). "FRA3B overlaps the FHIT gene, and FRA3B fragility often results in deletions of FHIT exons and loss of Fhit expression in precancer and cancer cells." (PMID 23209436, 2012). "Loss of Fhit protein in cancer is attributed to different genetic alterations that affect FHIT gene structure." (PMID 22295218, 2011). "Loss of Fhit protein in cancer is attributed to different genetic alterations that affect the FHIT gene structure." (PMID 22295218, 2011). "Deletions within FHIT have been associated with various human cancers including breast, lung, cervical, and esophageal." (PMID 21286310, 2010). "Because FHIT is a protein-coding gene with its ultimate product of fragile histindine triad protein that belongs to the histindine triad protein family with carcinoma suppression activity, FHIT gene mutation leads to FHIT protein abnormal expression." (PMID 18366613, 2008). "The higher frequency of alteration of FRA3B and reduced expression of Fhit in BRCA2-linked cancers was consistent with the idea that loss of BRCA2 function affects stability of the FRA3B/FHIT locus." (PMID 12771912, 2003). "FHIT knockout mice are much more susceptible to cancer induction than wild-type mice." (PMID 37634038, 2023). "However, the FHIT-deficient cancer cells can escape ROS overproduction and ROS-induced apoptosis, leading to the continued proliferation of cancer cells and eventually carcinogenesis." (PMID 36831487, 2023). "Abnormal FHIT expression is a molecular determinant of the “Catalog of Somatic Mutations in Cancer mutational signature 5”, which mainly occurs in the early stages of various cancers and accelerates carcinogenesis through oncogenic exposure." (PMID 36831487, 2023). "Consequently, it has been shown that FHIT-deficient cells are prone to acquire cancer promoting mutations and are more easily transformed in the presence of DNA damaging agents." (PMID 34092254, 2021). "Given the role of FHIT in early cancer initiation, it will be exciting to see if diagnostic tools for FHIT methylation could play a larger role in determining initial cancer development." (PMID 35663592, 2021). "In this commentary we discuss the importance of developing diagnostic tools for the early detection of FHIT methylation and the possibility that prior FHIT methylation may predispose any individual to the development of cancer." (PMID 35663592, 2021). "Whether FHIT methylation is the ultimate factor predisposing these individuals to carcinomas is unknown." (PMID 35663592, 2021). "The protein products of Fhit-regulated mRNAs function in a number of different pathways, the diversity of which may help explain the challenges encountered in identifying how FHIT loss leads to genome instability and cancer." (PMID 29282095, 2017). "In summary, FHIT is now considered as a cancer suppressor gene and the loss or aberrant transcripts of FHIT may be associated with carcinogenesis." (PMID 28036263, 2017). "We have presented data here that supports the hypothesis that FHIT loss is the underlying determinant of mutational signature 5, a signature that is ubiquitous in human cancers." (PMID 29254236, 2017).
cancer (continued). "WWOX and FHIT are tumor suppressor genes that are mutated in a wide range of cancers and could result in greater genomic instability given their roles in detecting genotoxic stress and regulation of the cellular response to genomic damage." (PMID 24454681, 2014). "Our results suggest that the cell-type specific depleted signals in cancer cell lines may be under genomic alterations and can be located near genes associated with different types of cancer (i.e. FHIT, STK11, CDKN2A, CDKN2B)." (PMID 25522020, 2014). "Thus, FHIT, which is reduced in expression in most human cancers, is a genome “caretaker” whose loss initiates genome instability in preneoplastic lesions." (PMID 24901304, 2014). "In addition, FHIT is a tumor suppressor that regulates a wide spectrum of biological processes associated with tumor initiation and progression, and FHIT expression is lost in many cancers." (PMID 25340791, 2014). "Moreover, a number of authors have shown that the suppressed transcription of WWOX and FHIT is associated with the more advanced stages in various types of cancer, including breast, non-small cell lung and ovarian cancers." (PMID 24137446, 2013). "If the FRA3B/FHIT locus is not the most fragile region in epithelial cells, then the fact that loss of heterozygosity at the FHIT gene is the most frequent alteration in cancer cells would suggest that loss of Fhit expression was a selected event in clonally expanded cells." (PMID 23209436, 2012). "Genetic and epigenetic alterations of FHIT are associated with development of several cancer types." (PMID 20163722, 2010). "Aberrant expression of the FHIT induces a level of genomic replication stress that leads to the generation of many DSBs and intrinsic errors of the DNA replication machinery, which increases the mutation rate in the cancer genome and provides opportunities for mutations to accumulate." (PMID 36831487, 2023). "Since its discovery, numerous studies have been conducted to elucidate the molecular mechanisms of FHIT in cancer." (PMID 39762409, 2025). "Fragile histidine triad (FHIT) has been documented to play a vital role in various cancers including acute lymphoblastic leukemia (ALL)." (PMID 38587694, 2024). "FHIT gene as reported is emerging as a putative therapeutic target not only for ALL but other cancer types as well." (PMID 38587694, 2024). "In this review, we summarized evidence of the FHIT from the perspective of cancer occurrence and the roles of the FHIT in various aspects of Cancer Evo-Dev." (PMID 36831487, 2023). "It is suggested that decreased FHIT expression is involved in several critical steps of Cancer Evo-Dev." (PMID 36831487, 2023). "Aberrant transcripts or decreases in the transcription and translation of the FHIT are present in at least 50% of preneoplastic lesions and human cancers, especially in esophageal, lung, liver, stomach, pancreatic, kidney, skin, breast, and cervical cancers." (PMID 36831487, 2023). "The FHIT protein also induces apoptosis in cancer cells by altering the mitochondrial transmembrane potential and enhancing cytochrome C efflux from mitochondrial cells." (PMID 36831487, 2023). "Normal human cells do not express hTERT; however, hTERT levels are elevated and negatively correlated with FHIT expression in cancers." (PMID 36831487, 2023). "Future research needs to focus on the role and mechanisms of the FHIT in promoting the transformation of pre-cancerous lesions into cancer." (PMID 36831487, 2023). "Decreased FHIT expression leads to the malignant transformation of affected cells and promotes the evolutionary development of cancer." (PMID 36831487, 2023).
cancer (continued). "Aberrant transcription or reduction in the transcription and translation of the FHIT is an early event occurring in at least 50% of preneoplastic lesions and human cancers." (PMID 36831487, 2023). "The top 10 frequently affected cancer-associated genes are HIRA (OG), CSMD1 (TS), CDH13 (TS), PRRX1 (OG), FHIT (TS), MGAM (OG), TBL1XR1 (OG), RHOA (OG), FGF14 (TS), and CNTNAP2 (TS)." (PMID 35013466, 2022). "Previously reported 4 cancer-specific methylated genes(DAPK, FHIT and TIMP3) were HPV-positive associated OPSCC markers." (PMID 36344942, 2022). "The tumor suppressor gene, Fragile Histidine Triad Diadenosine Triphosphatase (FHIT), is frequently lost in cancer through epigenetic modifications and/or deletion." (PMID 34092254, 2021). "Hypermethylation of FHIT is commonly detected in human cancers, resulting in its inactivation as a very early event in cancer formation." (PMID 34368151, 2021). "Based on host genome integration frequencies, we found previously reported integration sites in cancer for genes like FHIT, CSMD1, and LRP1B and putatively many new ones such as those exemplified in CSMD3, ROBO2, and SETD3." (PMID 33810183, 2021). "The aberrant methylation of other genes, such as FHIT, HOXA9, NNK, and MSH3 have also been found to be associated with cancer progression." (PMID 34456184, 2021). "The genomic identification of significant targets in cancer analyses (GISTIC) led to identify recurrent focal deletions (3p14.2 (FHIT), 11q11, and 4q13.2) and focal amplifications (17q13 (ERBB2), 8q24.21 (MYC), 3q26.31 (PIK3CA, TRAIL), 8q24.22, 8q21.13)." (PMID 32647357, 2020). "A total of 10 genes that were disrupted or within breakpoint‐associated TAD structures were classified as known (FHIT, FLCN, NCOA4, and RET) or candidate cancer genes (LLGL1, LRIG1, LYRM9, RASGEF1A, ST3GAL6, and TMEM199)." (PMID 31943436, 2020). "Two gain regions contained the well-known oncogenes EGFR (7p11.2) and CCND1 (11q13.3) and several known cancer suppressor genes, such as FHIT (3p14.2–p12.1), FAT1 (4q35.1), CDKN2A (9p21.3), and ATM (11q22.3–q24.3), reside within the 10 deletion regions." (PMID 31159251, 2019). "It is also noteworthy that 23 out of the 26 cancer samples had a breakpoint in the region of the gene FHIT lying inside of FRA3B." (PMID 31249626, 2019). "FHIT is a tumor suppressor gene, overexpressed in cancer; restoration of expression inhibits growth and induces apoptosis." (PMID 31766427, 2019). "We observed a bimodal distribution of APOBEC3B expression and unimodal distributions of APOBEC3A, REV1, UNG, and FHIT in the pan-cancer dataset." (PMID 29642934, 2018). "According to Kaplan-Meier plotter, we found that a higher FHIT expression was negatively correlated with overall and progression-free survival rates of all cancer patients, even stratified by aggressive parameters (p < 0.05)." (PMID 29296239, 2017). "Stage 0–I and 0–II cancers showed higher FHIT expression than stage II–IV (p = 0.0009) and III-IV (p < 0.00001) respectively." (PMID 29296239, 2017). "In summary, results presented here show that FHIT loss is associated with changes in ribosome occupancy of the 5’-UTR and/or coding region of 30 different mRNAs, many of which are associated with cancer." (PMID 29282095, 2017). "The pooled odds ratio of FHIT promoter methylation in cancer samples was 3.43 (95% CI: 1.85 to 6.36) compared with that in controls." (PMID 28036263, 2017). "According to Kaplan-Meier plotter, we found that a higher FHIT mRNA expression was negatively correlated with overall and progression-free survival rates of all cancer patients, even stratified by gender and Her2 status (p < 0.05)." (PMID 29296239, 2017). "FHIT was identified more than 20 years ago at a locus that is deleted or otherwise silenced in >50% of most human cancer types." (PMID 29282095, 2017).